GXYLT2 (glucoside xylosyltransferase 2)
Description:
Glycosyltransferase which elongates the O-linked glucose attached to EGF-like repeats in the extracellular domain of Notch proteins by catalyzing the addition of xylose.
Synonyms: GLT8D4
Tractability: Antibody: its Gene Ontology location is reachable by antibodies, with high confidence; UniProt predicts a signal peptide or a membrane-spanning region.
Gene: Protein-coding gene on chromosome 3 (72,888,046 to 72,998,138, forward strand). Ensembl gene ENSG00000172986.
Subcellular location: Membrane
Subcellular location (Human Protein Atlas): Nucleoplasm; Cytokinetic bridge; Midbody ring
Pathways (Reactome):
Developmental Biology: Regulation of MITF-M-dependent genes involved in extracellular matrix, focal adhesion and epithelial-to-mesenchymal transition
Gene Ontology:
Molecular function: UDP-xylosyltransferase activity; glycosyltransferase activity; UDP-D-xylose:beta-D-glucoside alpha-1,3-D-xylosyltransferase activity
Biological process: protein O-linked glycosylation via glucose
Cellular component: plasma membrane; membrane
Genetic constraint (gnomAD): Loss-of-function variants: 53 observed, 47.63 expected, observed/expected ratio (o/e) 1.11, 90% interval 0.89 to 1.4. The upper end of that interval is the gene's LOEUF score, 1.4, which puts it in group 5 of 6, group 1 being the genes least tolerant of losing a copy. Missense variants: 549 observed, 527.96 expected, observed/expected ratio (o/e) 1.04, 90% interval 0.97 to 1.12. Synonymous variants: 218 observed, 198.76 expected, observed/expected ratio (o/e) 1.1, 90% interval 0.98 to 1.23.
Homologues: Orthologues: macaque GXYLT2 (99% identical), chimpanzee PPP4R2 (93% identical), pig GXYLT2 (93% identical), dog GXYLT2 (91% identical), mouse Gxylt2 (88% identical), rat Gxylt2 (88% identical), guinea pig GXYLT2 (77% identical), rabbit GXYLT2 (75% identical), zebrafish gxylt2 (59% identical), tropical clawed frog gxylt2 (56% identical), Caenorhabditis elegans lge-1 (14% identical), Drosophila melanogaster CG9171 (12% identical), and 9 more. Paralogues in human: GXYLT1 (50% identical), LARGE1 (19% identical), LARGE2 (19% identical), XXYLT1 (18% identical), B4GAT1 (8% identical).
Diseases named in the same sentence as GXYLT2 in open-access papers:
GXYLT2 is named in the same sentence as 22 diseases in open-access papers, as found by Europe PMC text mining. Sharing a sentence is not in itself a finding about the gene and the disease. The quoted sentences say what the papers report.
gastric cancer (6 papers, 2021 to 2026). A primary or metastatic malignant neoplasm involving the stomach. "Taken together, the results suggested that GXYLT2 might be used as a diagnostic and prognostic marker in gastric cancer." (PMID 34506251, 2021). "Diagnostic meta-analysis results showed that GXYLT2 might be considered a diagnostic marker for gastric cancer and that GXYLT2 expression was remarkably correlated with poor survival prognosis and remarkably negatively correlated with the grade, depth of invasion and TNM stage in patients with GC." (PMID 34506251, 2021). "Hence, we hypothesized that GXYLT2 might be associated with GC progression and a prognostic marker of gastric cancer." (PMID 34506251, 2021). "In summary, GXYLT2 might be a potential diagnostic and prognostic biomarker for gastric cancer." (PMID 34506251, 2021). "Further research suggested that GXYLT2 was a reliable prognostic marker and correlated with tumor-infiltrating immune cells in gastric cancer." (PMID 36263004, 2022). "GXYLT2 expression was significantly correlated with the grade, stage, and invasion depth of gastric cancer." (PMID 34506251, 2021). "The results showed that the expression level of the GXYLT2 gene in gastric cancer cells was high, which verified the results of bioinformatics analysis." (PMID 34506251, 2021). "In this study, we confirmed that the expression level of GXYLT2 was higher in gastric cancer than in normal gastric tissues." (PMID 34506251, 2021). "The potential value of GXYLT2 in gastric cancer was comprehensively assessed, and the results were initially validated in vitro by performing qRT-PCR and immunohistochemistry assays." (PMID 34506251, 2021). "Through cell experiment verification, GXYLT2 expression level in gastric cancer cells was found to be high, which verified the results from the bioinformatics analysis." (PMID 34506251, 2021). "It indicated that GXYLT2 may participate vital immunity mechanistic pathways in tumorigenesis in gastric cancer." (PMID 36263004, 2022). "The results demonstrated for the first time that GXYLT2 might play a role during the process of the pathogenesis in gastric cancer via several signaling pathways, and the expression level of GXYLT2 was correlated with infiltrating immune cells." (PMID 34506251, 2021). "Based on these results, GXYLT2 was highly expressed in gastric cancer tissues." (PMID 34506251, 2021). "There are few studies on GXYLT2 in tumors, especially in gastric cancer." (PMID 34506251, 2021). "Therefore, GXYLT2 expression was positively correlated with M2 macrophages, which in turn accelerated the development of gastric cancer, leading to a poorer prognosis." (PMID 34506251, 2021). "Although GXYLT2 accelerates cell growth and migration in human cancer cells, to the best of our knowledge, there have been no reports on the role of GXYLT2 in the pathogenesis of gastric cancer." (PMID 34506251, 2021).
lymph node metastasis (2 papers, 2021 to 2022). "Univariate Cox regression analysis showed that age (P = 0.007), TNM stage (P < 0.001), lymph node metastasis (P = 0.0011) and GXYLT2 expression (P = 0.048) were significant factors affecting the survival time of patients with GC." (PMID 34506251, 2021). "The results showed significant associations between GXYLT2 expression and lymph node metastasis (p = 0.002) rather than distant metastasis (p = 0.233)." (PMID 36263004, 2022).
aneurysm (1 paper, 2019). Bulging or ballooning in an area of an artery secondary to arterial wall weakening. "We selected and validated the genes randomly (Lrrc17, Gxylt2, Mfsd2a, Scube and Ank2) and based on their role in aneurysms (Mmp12, Spp1, Ctss) or cardiovascular complications (Mfap4, Igfbp2) or inflammatory signalling pathways (Ccls and Ccrs)." (PMID 30677223, 2019).
Bladder Cancer (1 paper, 2022). "The hub genes of PPI network also indicated broad correlations between GXYLT2 and bladder cancer progression (such as cancer suppressor gene RPA2 and TUSC1." (PMID 36263004, 2022). "In the current study, we identified 16 immunostimulators related to expression of GXYLT2, and several of them were verified to be involved in the progression of bladder cancer in the previous studies." (PMID 36263004, 2022). "The data were collected with online public databases and the mechanism of GXYLT2 regulating the infiltration of immune cells in bladder cancer should be further examined by in vivo/in vitro experiments." (PMID 36263004, 2022). "To explore the functions and mechanism of GXYLT2, we analyzed the microenvironment surrounded by bladder cancer." (PMID 36263004, 2022). "Significant differences were observed between GXYLT2 expression of bladder cancer and normal tissues." (PMID 36263004, 2022). "By constructing GXYLT2 coexpression network in bladder cancer from TCGA database, we then performed functional enrichment analysis to elucidate gene function." (PMID 36263004, 2022). "Our study explored that the regulation of immune infiltration may engage GXYLT2 in progression of bladder cancer." (PMID 36263004, 2022). "GXYLT2 could be a promising therapeutic target in bladder cancer." (PMID 36263004, 2022). "The Cancer Genome Atlas (TCGA) was utilized to confirm relationships between GXYLT2 and molecular subtypes of BLCA (bladder cancer)." (PMID 36263004, 2022). "However, the correlation between GXYLT2 expression and bladder cancer remains unclear." (PMID 36263004, 2022).
bladder tumor (1 paper, 2022). "We also noticed that the mRNA expression of GXYLT2 was significantly associated with immune score of bladder tumor (p < 0.001)." (PMID 36263004, 2022). "Since these clinical features of bladder tumor are independent prognostic factors, we hypothesized that GXYLT2 may play a role in the outcomes of patients with BLCA." (PMID 36263004, 2022).
breast carcinoma (1 paper, 2021). "The results showed that GXYLT2 was highly expressed in GC cells and breast cancer cells and that GXYLT2 was mainly localized to the Golgi apparatus." (PMID 34506251, 2021). "In nude mice tumorigenesis experiments, the tumors formed by GXYLT2-overexpressing cells were smaller than those formed by control cells and knock down of GXYLT2 in breast cancer cells inhibited tumor formation." (PMID 34506251, 2021).
colorectal cancer (1 paper, 2021). A primary or metastatic malignant neoplasm that affects the colon or rectum. "GXYLT2 expression and cancer cell proliferation was decreased in acid-adapted colorectal cancer cells invasion was decreased, and tumor selectivity was high in acidosis compared with neutral healthy tissues." (PMID 34506251, 2021).
hepatic cancers (1 paper, 2020). "For instances, MGAT1, MGAT4A, and GXYLT2 are unfavorable prognostic markers, while MAN1C1, GCNT4, and STT3B are favorable markers in non-hepatic cancers." (PMID 32850363, 2020).
prostate carcinoma (1 paper, 2024). A carcinoma that arises from epithelial cells of the prostate gland. "KEGG analysis of mRNAs in the lncRNA-miRNA-mRNA regulatory network showed that GXYLT2 was enriched in other types of O-glycan biosynthesis, and AR was enriched in prostate cancer and oocyte meiosis pathways." (PMID 38649401, 2024).
cancer (8 papers, 2021 to 2026). A tumor composed of atypical neoplastic, often pleomorphic cells that invade other tissues. "To further understand the link underlying GXYLT2 and cancer patient outcome, we conducted survival analysis based on the Kaplan-Meier Plotter database, LinkedOmics database, and GEPIA database, respectively." (PMID 36263004, 2022). "Previous researchers have studied GXYLT2 in GC, primarily by comparing the expression level differences between tumor and normal tissues, and they indicated that GXYLT2 played a pro-cancer role in GC." (PMID 41492474, 2026). "The Drosophila GXYLT (Shams) transferred xylose onto a specific subset of Notch EGF repeats for negative regulation of Notch signaling, while human GXYLT2 activated Notch1 signaling to promote cancer cell proliferation and invasion." (PMID 41492474, 2026). "GXYLT2 depletion not only significantly reduced cancer cell proliferation but also suppressed the cell invasiveness of all three GC cell lines." (PMID 41492474, 2026). "We firstly examined the expression of GXYLT2 across different human cancers by using ONCOMINE database." (PMID 36263004, 2022). "Previous study revealed that GXYLT2 promoted human cancer cells growth, migration, and invasion activity." (PMID 36263004, 2022). "Xylose modification of Notch by GXYLT1 and GXYLT2 suppresses Notch activity in Drosophila, whereas xylosylation by GXYLT2 upregulates the Notch pathway in human cancers." (PMID 35459861, 2022). "GXYLT2 promotes the proliferation and migration of human cancer cells by regulating the NOTCH signaling pathway." (PMID 34195091, 2021). "Knock down of GXYLT2 significantly inhibited the proliferation and migration of cancer cells." (PMID 34506251, 2021). "Five—Using STRING database, we found that it had interactions with several proteins involved in different cancers such as TXNDC9, GXYLT2, POFUT1, XXYLT1, FLNA, and ZC3H12C." (PMID 35140741, 2021). "Altogether, these results indicated that GXYLT2 was required for the proliferation, invasion, and sphere-forming capability in diffuse-subtype GC cells, but not in intestinal-subtype cancer cells." (PMID 41492474, 2026). "In our pilot study, the expression levels of GXYLT2 were significantly different between GC tissue and nor normal gastric tissue by analyzing the data from the TCGA (The Cancer Genome Atlas) database and GEO (Gene Expression Omnibus) database." (PMID 34506251, 2021).
tumor (6 papers, 2021 to 2026). "Among them, the overexpression of glucoside xylosyltransferase 2 (GXYLT2) was positively associated with tumor stage, diffuse subtype, and unfavorable survival outcomes in GC patients." (PMID 41492474, 2026). "The results suggested that GXYLT2 was associated with a poor prognosis and tumor immune cell infiltration of BLCA." (PMID 36263004, 2022). "At the experimental endpoint, tumors were harvested, and tumor weight of control group was remarkably higher than that of GXYLT2 knockdown group (sh2; p < 0.01)." (PMID 41492474, 2026). "The changes in GXYLT2 mRNA levels across different tumor stages, tumor grades, family history of GC, and H. pylori infection status were analyzed based on patients' age in the TCGA-STAD dataset." (PMID 41492474, 2026). "In contrast, eight genes (COL1A1, COL5A1, COL1A2, COL3A1, WNT2, C1QTNF3, ADAMTS2, GXYLT2) exhibited elevated expression in tumor compared to normal tissue." (PMID 39062832, 2024). "GXYLT2 expression was significantly correlated with tumor purity as well as CD8+, macrophages, neutrophils, and dendritic cells (p < 0.001)." (PMID 36263004, 2022). "The results of clinical characteristics analysis also showed that the grade and stage of tumor had remarkable relationship with GXYLT2 expression." (PMID 36263004, 2022). "Subsequently, correlations between GXYLT2 and tumor immune infiltration were investigated through TIMER and TISIDB website." (PMID 36263004, 2022). "TA total of 375 GC patients with adjust P < 0.05 were selected for the following analysis, the correlation of 22 tumor-infiltrating immune cells analysis demonstrated the relationship between the GXYLT2 expression and immune cells infiltration." (PMID 34663825, 2021). "The results of the differences and correlation between GXYLT2 expression and tumor-infiltrating immune cells showed that 11 tumor-infiltrating immune cells were significantly correlated with GXYLT2 expression." (PMID 34506251, 2021). "The correlation between GXYLT2 and tumor immune cells was identified by using the CIBERSORT algorithm." (PMID 34506251, 2021). "The staining results showed that GXYLT2 was mainly expressed in the cytoplasm and membrane of tumor cells." (PMID 34506251, 2021). "The high expression level of GXYLT2 was essentially identified with tumor grade (P = 0.029), pathological stage (P = 0.036), and T classification (P = 0.023)." (PMID 34506251, 2021). "We also found that GXYLT2 depletion could only suppress the tumor aggressiveness of the diffuse-subtype GC cells." (PMID 41492474, 2026). "Taken together, we identified GXYLT2 as a potential prognostic biomarker for GC patients, and targeting GXYLT2 suppressed the tumor aggressiveness and inhibited the Wnt/β-catenin pathway, which may provide a potential therapeutic target for GC patients." (PMID 41492474, 2026). "Targeting GXYLT2 suppressed the tumor aggressiveness and inhibited β-catenin activation." (PMID 41492474, 2026). "We found that GXYLT2 was closely related to tumor immune infiltrated cells and immune genes." (PMID 36263004, 2022). "GXYLT2 was demonstrated to be close relationship with various tumor immune cells." (PMID 36263004, 2022). "Enrichment analysis showed that GXYLT2 might participate in the development of GC through cell adhesion molecules and tumor-related pathways." (PMID 34506251, 2021). "Further, GXYLT2 expression was correlated with tumor-infiltrating immune cells in GC patients." (PMID 34506251, 2021). "Since GXYLT2 was previously shown to activate Notch1 signaling by up-regulating Hes family bHLH transcription factor 1 (HES1) to facilitate tumor progression, we investigated whether the suppressive effects of GXYLT2 knockdown on GC aggressiveness were related to Notch1 signaling." (PMID 41492474, 2026). "These indicated that GXYLT2 may play a vital role in human tumor progression." (PMID 36263004, 2022). "GSEA showed that GXYLT2 might participate in the development of GC through tumor-related pathways." (PMID 34506251, 2021).
tumor (continued). "A total of six types of tumor immune cells including B cell, CD8+ T cell, CD4+ T cell, macrophage, neutrophil, and dendritic cell were analyzed for the correlation with GXYLT2 expression in BLCA." (PMID 36263004, 2022). "GXYLT2 is considered an important gene that regulates canonical Notch signaling, participates in human tumor progression, and is closely related to tumor immune infiltrating cells and immune genes." (PMID 38649401, 2024).
GXYLT2 also shares sentences with these, for which no sentence is quoted: atherosclerosis (1 paper); colon adenocarcinoma (1); dental caries (1); head-neck squamous cell carcinoma (1); infection (1); lymphoma (1); melanoma (1); osteoporosis (1); prostate adenocarcinoma (1); uterine corpus endometrial carcinoma (1); viral infection (1).